IL3 (interleukin 3)
Diseases named in the same sentence as IL3 in open-access papers (continued):
Sharing a sentence is not in itself a finding about the gene and the disease.
infection (continued). "In this study, expression levels of IL-4, IL-10, IL-13 and TNF-α were significantly up-regulated while the expression levels of IL-1β,IL-18,IFN-γ, IL-2, IL-15, IL-17F, IFN-α, IFN-β, IL-3 and CSF-1 were markedly decreased in PBMCs at all stages of infection." (PMID 24358317, 2013). "The levels of IFN-β, IL-3 and CSF were significantly decreased at 7 and 14 days after infection and then moderately increased at 21 and 28 dpi." (PMID 24358317, 2013). "Following infection, S0 cells were cultured for 15 h in IL-3 and SCF and then transferred to Epo for 24 h, when CD71/Ter119 and cell cycle profiles were examined." (PMID 20877475, 2010). "Infection with M. fermentans or M. penetrans prevented apoptosis and effectively induced IL-3 independent growth of the cells." (PMID 16674811, 2006). "Infections by the transforming mycoplasmas upregulated c-Myc expression and partially compensated the decrease of c-Myc expression following IL-3 withdrawal." (PMID 23675000, 2006). "Similarly, CD131, which is shared by GM-CSF, IL-3, and IL-5 signaling, was expressed in most developmental stages and was markedly enhanced upon infection." (PMID 39868131, 2025). "A wide range of cytokines, such as IL-3, IL-11, and granulocyte–macrophage colony-stimulating factors, as well as thrombopoietin and IL-6, are involved in stimulating platelet production in response to infection." (PMID 40427060, 2025). "Thirteen of the tested proteins (G-CSF, GM-CSF, M-CSF, TNF-β, IFN-gamma, TNF-α, IL-1 β, IL-3, IL-6, IL-7, IL-15, IL-17, IL-19) were found in the hemolymph and hemocytes of G. mellonella; however, the results regarding the influence of infection differed according to the detection method." (PMID 38774871, 2024). "Additionally, a substantial increase in IL-17A, CCL11 and IL-3 were observed in the plasma of c-Flip+/–mice on day 2 and day 6 post-infection." (PMID 39038037, 2024). "Furthermore, IL-3 expression, a basophil growth factor also involved in infection-induced response of immune cells, was up-regulated by all peptides stimulation." (PMID 36248729, 2022). "Interestingly, microscopic analysis revealed that the frequency of GFP+ parasitic adults in the small intestine (85.8% ± 2.94%) did decline relative to the frequency of GFP+ iL3 used for infection (94.3%)." (PMID 34237106, 2021). "We found that many cytokines messenger RNAs (mRNAs), including Il1b, Il5, Il6, Il10, Il12a/Il12p70, Ifng, Ccl4, Ccl5, Tnfa, Gcsf, Cxcl1, Il1a, and Il3, were significantly induced upon B.1.351 infection in the lungs of hACE2 transgenic, BALB/c, and C57BL/6 mice." (PMID 34907154, 2021). "After infection with LVS, six cytokines were significantly higher in wild-type BMDM cultures with immune vs. naïve splenocytes, whereas in cultures with GBP-deficient BMDM IL-2 and IL-3 were higher and IL-4 lower with immune vs. naïve splenocytes." (PMID 33363054, 2020). "However, CD4+ T cell depletion decreased production of IL-2 and IL-10 in early stage infection, decreased production of IL-17 and TNF-α, and abolished IL-3 production in both early and late stage infection." (PMID 31608052, 2019). "However, following infection, we observed significantly elevated levels of IL-1β, IL-2, IL-3, IL-5, IL-6, IL-10, IL-17A, MIP-1α, MIP-1β, KC, transforming growth factor β (TGF-β), G-CSF, and GM-CSF in HO-1−/− mice compared to HO-1+/+." (PMID 30428359, 2018). "A crucial factor in this process was the well-adapted host–parasite pairing represented by S. ratti in the rat, in which the efficiency of infection is ~50% allowing successful host passage of the very small numbers of transgenic iL3 available in the first three generations of line establishment." (PMID 27000743, 2017). "Once derived, iL3 of P. trichosuri undertake a canonical pattern of parasitic nematode development with percutaneous infection followed by tissue migration that culminates in population of the intestinal tract with adult male and female parasites and release of eggs in host feces." (PMID 27000743, 2017).
infection (continued). "Based on the role of Δ7-DA in promoting continuous development in C. elegans, we hypothesized that biosynthesis of this or other Ss-DAF-12 ligand(s) is necessary for resumption of development by S. stercoralis iL3 at the time of infection." (PMID 26727267, 2016). "Specifically, TNF-α, GM-CSF, MIP-1α, IL-1α, IL-1β, IL-2, IL-3, IL-12p40, IL-12p70, and IL-17 levels were significantly reduced in UV-12 animals compared to vehicle control treated mice at both the 72 and 96 h post infection time points." (PMID 25984714, 2015). "Expression levels of interleukin (IL)-4, IL-10, IL-13 and tumor necrosis factor (TNF)-α were significantly up-regulated while interferon (IFN)-α, IFN-β, IFN-γ, IL-1β,IL-2, IL-3, IL-15, IL-17F, IL-18 and colony-stimulating factor (CSF)-1 were markedly decreased in PBMCs at all stages of infection." (PMID 24358317, 2013). "Like IL-12, other traditional TH1 cytokine: IL-3, M-CSF, and GM-CSF can also cause macrophage proliferation but these genes are also not up-regulated in response to infection with P. falciparum." (PMID 24188121, 2013). "Strong support for this hypothesis came from studies demonstrating that the IL-3-dependent cell line BaF3 could be converted to factor-independence by SFFV-P infection if and only if a construct driving exogenous expression of the EpoR was introduced." (PMID 21994618, 2010). "Infection by M. fermentans or M. penetrans not only alleviated the sharp decrease of c-Myc expression, rescued 32D cells from cell-cycle arrest and prevented apoptosis in IL-3-free culture, but also induced autonomous growth of 32D cells." (PMID 23675000, 2006). "IL-5, IL-4, and IL-3 could attenuate the anti-Candida response in the WT-infected group, and a combination of both allows the fungal cells to thrive and induce tissue damage and death within 8 days of WT infection." (PMID 38783167, 2024). "Some studies suggested that system or local infection could increase release of thrombopoietin and different inflammatory cytokines, such as IL-1, IL3 and IL6 and tumor necrosis factor-α, result in increasing thrombopoiesis and lead to the production of younger large platelets in blood circulation." (PMID 35614411, 2022). "Extending this analogy to S. stercoralis, we hypothesized that cytochrome P450 activity is required for endogenous biosynthesis of DA(s) or related Ss-DAF-12 ligand(s) and that inhibition of this activity would block resumption of development by iL3 at the time of infection." (PMID 26727267, 2016). "Given that GM-CSF and IL-3 are part of the ‘cytokine storm’ that correlates with infection-related disease severity and death, these data indicate that lower levels of GM-CSF and IL-3 may have contributed to the delayed time-to-death observed following infection with either ΔfmvA or ΔfmvB." (PMID 27513341, 2016). "In the present study, haemonchosis elevated IL-3, IL-6, IL-10, and TNF-α gene expressions in abomasum tissue mRNA, which was attributed to the activation of the inflammatory cascade triggered by infection." (PMID 38963478, 2024). "Early after infection (day 4 PI), plasma levels of IFN-γ, TNF-α, IL-3, IL-17, IL-1β, and IL-4 were increased in baso IL-18R (−) mice but not in basophil-depleted mice." (PMID 38780542, 2024). "We propose that upon infection of the mammalian host the Δ4-DA, contained in the serum, directly activates DAF-12 to readily trigger iL3 development, the starting point for adult parasite installation in the mammalian host." (PMID 37339136, 2023). "However, the role of IL-3 (also affected by G9P infection) in RVA infection remains unknown." (PMID 37515094, 2023). "Although HCMV can induce IL-3 secretion during early infection of MRC-5 cells, it has been observed that during prolonged infection, IL-32 transcript as well as protein levels were decreased with increasing miR-UL112-1 expression." (PMID 37896804, 2023).
infection (continued). "According to a previous study published in 1997, the authors found that IFN-γ, IL-2, IL-3, IL-4, and IL-5 were significantly changed in BALB/c mice after infection with a small amount of H. nana (100 eggs/mouse) at 14 days." (PMID 35878385, 2022). "One study showed that tick infection can generate IL-3+ CD4+ TRMs distant from the primary tick infection site, potentially leading to efficient control at re-infection." (PMID 34445713, 2021). "Upon infection, TNF-α, IL-4, and IL-6 expressions heightened, while IL-3 and IL-1β only appeared in trace amounts." (PMID 32943637, 2020). "During infection, CSF3 works along with IL3, IL6, and CSF2 to stimulate neutrophil granulopoiesis in the bone marrow to restore neutrophil homeostasis." (PMID 33362771, 2020). "Following infection, expression levels of the immunomodulatory cytokines C-C motif chemokine 22 (CCL22), CCL1, IL-23α, IL-3, IL-4, matrix metalloproteinase 9 (MMP9), IL-21, C-X-C motif chemokine 2 (CXCL2), and CCL2 were increased." (PMID 28507072, 2017). "In the sera of M. fortis, the levels of IL-1b, IL-3, IL-4, IL-10, IL-17, MCP-1 and VGF were found to increase from the second to the third week post-infection." (PMID 28900150, 2017). "However, some general points can be made: Th2-associated cytokine levels were higher overall, as might be expected given the nature of the infection; IL-3, IL-4, IL-5, IL-10 and IL-13, were all elevated in popLN cells from infected limbs, particularly so when re-stimulated with Brugia antigen." (PMID 27992545, 2016). "Historically, low levels of T cell cytokines (IL-2, IL-3, IL-4, IL-5, IL-9, IL-13) have been observed in fatal human cases of infection with EBOV and in infection of NHPs with MARV." (PMID 26512687, 2015). "The first peak occurred early during infection, over days 3–7 post-challenge (CSG IL1 and IL6), while the second wave occurred during acute symptomatic infection over days 10–14 post-challenge (CSGs IL2, IL3, IL7–IL10)." (PMID 25014551, 2014). "The R2 of 0.683 suggests that levels of IL-5 and IL-3 and an environmental variable (i.e., the distance from the water source to the toilet) explained 68.3% of stunted children with STH infection; the remaining 31.7% were influenced by other factors that were not considered." (PMID 38393122, 2024). "Whole-kidney levels of other neutrophil-recruiting (IL-3, GM-CSF) or inhibitory cytokines (IL-4, IL-10) were not significantly altered by androgen exposure at measured time points after infection (data not shown)." (PMID 38206009, 2024). "Furthermore, we observed a significant increase in TNFα, IL-1α, IL-2, IL-3, IL-4, IL-9, IL-10, IL-12 (P70), IL-17A, and CCL5 on day 4 post-infection in murine macrophages." (PMID 39038037, 2024). "More importantly, both SARS-CoV-2 and pCoV-GD01 infection induced the production of cytokines such as IFN-gamma, IL-12p70, IL-13, IL-2, IL-5, TNF-alpha, IL-17A, IP-10, MCP-3, MIP-1beta, MIP-2, Exotaxin, IL-15/15R, IL-28, IL-3, G-CSF, IL-1alpha and ENA-78." (PMID 37330497, 2023). "Plasma cytokines (IL-1β, IL-3, IL-6, IL-8, IL-18, IP-10, MIG, TNF-α, IFN-γ, MIP-1α and MIP-1β) and total peroxide (TPX) levels were quantified at baseline and at months 1 and 6 after the onset of the infection." (PMID 37894054, 2023). "Heightened colonic cytokine levels in the WT-infected group also correlated with significant increases in serum GCSF, IL-1β, IL-3, IL-6, IL-17, CXCL1, CXCL9, MCP-1, TNF-α and TREM at the peak of infection (48-hours), when compared to the TcdA−TcdB−CDT+ and uninfected groups (p< .05)." (PMID 36045589, 2022). "In immunocompetent patients, well-regulated autoinfective cycling of S. stercoralis can maintain chronic subclinical infection for decades without further input if iL3 from the environment." (PMID 31929961, 2019). "Mouse infection models using BCG or HSV-2 showed that cutaneous infection with these microbes led to the generation of IL-3–producing CD4+ T cells, whereas i.v. infections did not." (PMID 31356170, 2019).
infection (continued). "Prolonged infections with these mycoplasmas eventually lead to autonomous growth of the cells in vitro and to form tumors in mice in the absence of either IL-3 or the transforming mycoplasmas." (PMID 16674811, 2006). "Compared to the non-infection group, we observed elevated levels of the majority of measured cytokines (25/48) in the CSF during Mtb infection, including TNF-α, IFN-γ, IL-1β, IL-2, IL-3, IL-6, IL-8, IL-10, IL-12(p40), IL-17A, IL-18, IP-10, MIG, MCP-3, MIP-1α, and MIP-1β." (PMID 38047697, 2024). "Levels of six other chemokines and cytokines (IL-5, IL-1α, IL-3, G-CSF, IL-9, and eotaxin) were modestly increased or not increased with infection over time, but were reduced in basoIL-18R (−) mice relative to basoIL-18R (+) mice at 4 d PI (IL-5) or at 10 d PI (IL-1α, IL-3, G-CSF, IL-9, eotaxin)." (PMID 35985797, 2022). "Moreover, upon infection, several species of human Mycoplasmas would prevent apoptosis in 32D cells from undergoing in vitro in the absence of IL-3, indicating continuous growth even in the absence of the important IL-3 growth signaling." (PMID 32899663, 2020). "Apoptotic cells in IL-3 free cultures infected with M. fermentans or M. penetrans were about 70% and 50% respectively less than those found in non-infected control cultures 24 h following the infection." (PMID 23675000, 2006). "The lack of detection of VEGF-C, VEGF-D, IL-3 or IL-7 may be because we were examining the production of these molecules by PBMCs which may not be the cellular source; these molecules may be produced by a cell found focally at the infection site." (PMID 25010672, 2014). "Plasma levels of six cytokines (IL-2, IL-3, IL-4, IL-7 and VEGF) were not significantly altered by Kp-1705 infection nor were they affected by MTD12813 treatment." (PMID 34873199, 2021). "Similar to WT mice, in the CNS of Rag1−/− mice IFN-α1, IFN-β, TNF, IL-1α, IL-1β, IL-6, and IFN-γ mRNA levels increased following i.c. infection with ZIKV, and IL-2, IL-3, IL-4, and IL-5 mRNA was not detectable (data not shown)." (PMID 31511023, 2019). "For those plasma cytokines and chemokines with no sex-specific differences over the course of infection, a majority, including IL-2, IL-10, IFN-γ, MIP-1α, IL-3, IL-4, IL-5, IL-12p70, IL-13, IL-17, and G-CSF, exhibited differing temporal patterns between genotypes." (PMID 35970557, 2022). "The Epo-dependent erythroleukemia cell line HCD-57 can grow in the absence of Epo after infection with either SFFV-P or SFFV-A, but only SFFV-P can confer factor-independence to BaF3-EpoR cells, an IL-3 dependent hematopoietic cell line that has been engineered to express the Epo receptor (EpoR)." (PMID 21994618, 2010).
cancer (82 papers, 2012 to 2026). A tumor composed of atypical neoplastic, often pleomorphic cells that invade other tissues. "The AML also lost mutations in cancer genes toward the end of treatment in comparison with initiation, e.g., in IL3 (p.P27S, VAF 9.3%) and NCOR2 (p.G1830delinsSSGG, VAF 19.6%)." (PMID 38012682, 2023). "The remaining EGFR variants transformed Ba/F3 cells and demonstrated similar doubling time to that of the parental cells provided IL‐3, indicating that these cancer‐derived variants are indeed EGFR activating mutations." (PMID 31314158, 2019). "Aberrant expression of IL-3 is associated with angiogenesis, chronic inflammation and cancer." (PMID 24658545, 2014). "Normal PBMCs to C1D1 PBMCs revealed changes in IL-3 signaling, Fcγ receptor-mediated phagocytosis, and molecular mechanisms of cancer." (PMID 42075799, 2026). "Certain proinflammatory cytokines, including IL‐1, IL‐3, and IL‐6, induce thrombopoiesis in cancer patients." (PMID 39102040, 2024). "Previous clinical trials have demonstrated that IL-3 can elevate peripheral platelet and neutrophil counts and mitigate chemotherapy-induced myelosuppression in cancer patients suffering from bone marrow failure and undergoing chemotherapy." (PMID 38256942, 2024). "IL3 was part of a 15-gene panel consistently overexpressed in bone metastases across various cancer types." (PMID 39125732, 2024). "The basophils in TDLNs were observed, and the role of cancer-associated fibroblasts in releasing TSLP was noted, which in turn activated dendritic cells (DCs) to generate IL-3 from CD4* T cells." (PMID 39816393, 2024). "Fusion of a fragment of the target cancer receptor interleukin 3 (IL3) with Lamp2b allows for exosomal targeted cancer therapy." (PMID 37514088, 2023). "IL-3 plays a vital role in the extravasation of cancer cells by promoting the production of matrix metallopeptidase 2 (MMP-2) by cancer cells, enhancing the invasiveness of cancer cells." (PMID 37056723, 2023). "IL-3 induced morphological changes in cancer cells, translating in their ability to form tube-like structures." (PMID 36010912, 2022). "IL-3 has been reported to exert paradoxical effects in cancer including pro-tumourigenic as well as anti-tumourigenic cellular responses." (PMID 32694701, 2020). "From a molecular cancer point of view, thrombocytosis has been illustrated to be stimulated by cancer-mediated production of cytokines, most commonly interleukins (IL-1, IL-3, IL-6, and IL-9) and granulocyte-macrophage colony-stimulating factor (GM-CSF)." (PMID 29736362, 2018). "Inflammatory cytokines released by various cancer entities, like IL-3, IL-6, and IL-10, are capable of stimulating megakaryocytes proliferation, which can produce platelets." (PMID 30643825, 2018). "Mast cells play a key role in the pathogenesis of cardiovascular diseasesand cancers via secreting a variety of cytokines includingTNF-α, IL-3, IL-4, IL-5, IL-6, IL-10, IL-13, IL-14 and IL-16." (PMID 26625310, 2016). "5637, which is a Grade-II carcinoma, was originated from a 68-year-old male in 1974, and can secrete some cytokines, including growth factor, G-CSF, GM-CSF, IL-3, etc7." (PMID 25752336, 2015). "Many pathways were perturbed in almost all the cancers, with p-value less than 0.01: IL-3 pathway, IL-2 pathway, TNF-alpha Pathway EGFR1 pathway, TGF-beta receptor pathway, Alpha6 Beta4 Integrin pathway, and B Cell Receptor pathway." (PMID 22536907, 2012). "Therefore, fusion proteins involving IL-3 and GM-CSF have been designed to prevent thrombocytopenia in chemotherapy-treated patients with certain cancer types." (PMID 39447666, 2024). "Furthermore, cancer cells secrete interleukin 3 (IL-3), stimulating ECs to secrete EVs that further promote neovessel formation." (PMID 37946275, 2023). "Following IL-3 withdrawal, cancer cells could be removed after phagocytosis by resident macrophages." (PMID 37551318, 2022). "Interleukin-3, 5 and GM-CSF signaling and Pathways in cancer." (PMID 28477017, 2017).